KPNB1 (karyopherin subunit beta 1)
Diseases named in the same sentence as KPNB1 in open-access papers (continued):
Sharing a sentence is not in itself a finding about the gene and the disease.
infection (8 papers, 2011 to 2025). The state of being infected such as from the introduction of a foreign agent such as serum, vaccine, antigenic substance or organism. "To dissect the role of KPNB1 in the cell cycle regulation, we first generated KPNB1-deficient U87 and U251 cells by the infection of shKPNB1s-encoding lentiviruses." (PMID 29520102, 2018). "KPNB1 depletion had a smaller effect on HIV-1WT infection in HT1080 cells but caused a large accentuation of MX2 activity." (PMID 30084827, 2018). "HIV-1N57S was strikingly inhibited by KPNB1 depletion, and the ability of MX2 to reverse CypA induced inhibition of HIV-1N57S infection was abolished by KPNB1 depletion." (PMID 30084827, 2018). "At early infection stage (at 24 h post infection), genes contributing to the nuclear transport like KPNA2 and KPNB1, RNA splicing gene SF3B4 were down-regulated compared with the normal control." (PMID 23451031, 2013). "In addition, the expression levels of KPNB1, KPNA1, KPNA2, KPNA4, KPNA6, and KPNA7 changed with the infection time of the three strains while KPNA3 and KPNA5 did not change with the incubation time." (PMID 40687856, 2025).
mental illnesses (1 paper, 2025). "However, there is currently limited research on whether the KPNB1 gene can serve as a specific diagnostic biomarker for mental illnesses to further investigate related therapeutic targets, especially for DD." (PMID 40370665, 2025).
neurodegenerative disease (1 paper, 2013). A disorder of the central nervous system characterized by gradual and progressive loss of neural tissue and neurologic function. "The lack of KPNB1 has been reported in Aβ-treated cells as well as varieties of mental and neurodegenerative diseases." (PMID 24386444, 2013).
KPNB1 also shares sentences with these, for which no sentence is quoted: B-cell lymphoma (2 papers); acute myeloid leukemia (1); benign skin nevus (1); colon cancer (1); Dengue fever (1); esophageal carcinoma (1); hepatocellular carcinoma (1); lymphoma (1); metabolic disease (1); multiple myeloma (1); nervous system tumors (1); neuropathic pain (1); nevus (1); pancreatic ductal adenocarcinoma (1); peripheral neuropathy (1); polycystic ovary syndrome (1); spinocerebellar ataxia (1); viral infection (1).